IL18 (interleukin 18)
Diseases named in the same sentence as IL18 in open-access papers (continued):
Sharing a sentence is not in itself a finding about the gene and the disease.
tongue squamous cell carcinoma (3 papers, 2015 to 2022). A squamous cell carcinoma that arises from the tongue. "The aim of this study was to investigate the effects of interleukin-18 (IL-18) expression on regulating the viability and apoptosis of tongue squamous cell carcinoma (TSCC) cells in vitro and examine the underlying molecular events." (PMID 25591548, 2015).
toxoplasmosis (3 papers, 2017 to 2021). A parasitic disease contracted by the ingestion or fetal transmission of toxoplasma gondii. "While there is evidence that pro-IL-1 and pro-IL-18 are produced during toxoplasmosis, several studies have concluded that T. gondii does not readily activate inflammasomes and there is evidence that Toxoplasma suppresses inflammasome activity." (PMID 33929319, 2021). "To definitively assess if IL2C-mediated expansion of IL-18-responsive IFN-γ-secreting non-CD4 cell subsets can prevent lethal toxoplasmosis in mice, we used the well-established oral inoculation model with T. gondii ME49 bradyzoite-containing brain cysts." (PMID 32753607, 2020). "Collectively, these results demonstrate a protective role of IL2C pre-treatment in acute lethal murine toxoplasmosis that is dependent on IL-12, IL-18 and IFN-γ but is independent from effects on parasite burden." (PMID 32753607, 2020).
tularemia (3 papers, 2011 to 2016). Tularemia is an infection caused by the bacterium Francisella tularensis. "Of note, inflammasome-mediated resistance to Francisella tularensis is mediated by both IL-1β and IL-18, and mice deficient in either cytokine are resistant to tularemia, while those deficient in both IL-1β and IL-18 are sensitive." (PMID 22241984, 2011). "Thus, different mechanisms determine the increased susceptibility of Il-1r1-/- and Il-18-/- mice to tularemia." (PMID 25768794, 2015). "IL-18-deficient mice quickly succumbed to infection with high organ bacterial burdens and low levels of IFNγ, a cytokine that has been shown to be critical for protection from tularemia." (PMID 25768794, 2015). "Administration of IFNγ rescued the survival of Il-18-/- mice, suggesting that their decreased resistance to tularemia is due to inability to produce IFNγ." (PMID 25768794, 2015). "Administration of IFNγ increased the survival of Il-18-/- mice, suggesting that the lower resistance to tularemia is due to an inability to produce IFNγ." (PMID 25768794, 2015). "Our results also suggest that the diminished levels of IL-1β and IL-18 in the lungs of Nlrp3-/- mice may be sufficient to support their critical protective function during pulmonary tularemia." (PMID 27926940, 2016). "Collectively, these studies indicated that IL-1β and IL-18 may contribute to protection from tularemia but it remains unclear to what extent, through which mechanism, and under which conditions." (PMID 25768794, 2015). "As IL-1β/IL-18 levels are reduced in Ft LVS infected Nlrp3-/- mice, the amounts of these cytokines required for protection during pulmonary tularemia may be much lower than previously thought." (PMID 27926940, 2016). "Collectively, our results show that IL-1β and IL-18 activate non-redundant protective responses against tularemia and identify an essential role for IL-1β in the rapid generation of pathogen-specific IgM by B1a B cells." (PMID 25768794, 2015).
uremia (3 papers, 2022 to 2026). A clinical syndrome associated with the retention of renal waste products or uremic toxins in the blood. "The most important is the lack of determination of more serum inflammation (IL-6, IL-10, IL-18, TNF-α), bone metabolic (FGF-23 and bone alkaline phosphatase), and uremia markers." (PMID 36611532, 2022).
vaginal candidiasis (3 papers, 2014 to 2020). "As deficiency in IL-18/IL-22 crosstalk is associated with impaired Th/Treg cell development and increased VVC susceptibility, IL-18 appears to act as a bridge between innate and adaptive immunity during vaginal candidiasis." (PMID 31972980, 2020). "Similarly, while caspase-1-dependent secretion of the proinflammatory cytokines interleukin-1β (IL-1β) and interleukin-18 (IL-18) has potent antifungal properties, symptoms of vaginal candidiasis are largely caused by sustained influx of neutrophils due to IL-1β secretion." (PMID 25057992, 2014).
varicocele (3 papers, 2020 to 2025). A condition characterized by the dilated tortuous veins of the spermatic cord with a marked left-sided predominance. "In this study, we analyzed relationship of spermparameters with NLRP3, ASC, IL-18 and caspase-1 inboth control and varicocele groups." (PMID 32112635, 2020). "In this study, we expected that IL-18 level wouldbe increased in varicocele subjects, while it wasdecreased." (PMID 32112635, 2020). "Additionally,concentration of IL-1β was higher in varicocele versuscontrol subjects, whereas IL-18 was decreased in seminalplasma of varicocele patients and caspase-1 was notchanged." (PMID 32112635, 2020).
Yersinia infection (3 papers, 2015 to 2024). "Nonetheless, IL-18 levels during ΔyopEH Yptb infection were significantly lower than IL-18 levels released during Δ6 Yptb infection, suggesting that additional Yops contribute to inflammasome evasion during Yersinia infection of human IECs." (PMID 37615436, 2023). "IL-18 has been shown to be required for host protection during Yersinia infection." (PMID 26468944, 2015). "However, neither LPS+IKKi treatment nor Yersinia infection induced IL-18 release in THP-1 macrophages, suggesting that human macrophages do not undergo pyroptosis or inflammasome activation in response to IKK blockade." (PMID 39186805, 2024).
abortion (2 papers, 2017 to 2023). the ending of pregnancy by removing a fetus or embryo before it can survive outside the uterus. "IL-18 is expressed at the maternal–fetal interface at the chorion and decidua levels Increased expression at this level has been associated with an increased risk of preterm delivery, as well as recurrent spontaneous abortion." (PMID 37373945, 2023).
acute leukemia (2 papers, 2017 to 2020). A clonal (malignant) hematopoietic disorder with an acute onset, affecting the bone marrow and the peripheral blood. "It is useful to do biological activity of IL-18 as well as KG-1 cell line, which is a human acute leukemia and a standard to validate it by secreting IFN-γ in culture media." (PMID 31963531, 2020). "Serum samples from CRMO patients contained higher concentrations of CCL4/MIP-1β, CCL5/RANTES, CCL11/eotaxin, S100A8, and lower concentrations of IL-18, sIL-2R, and osteoprotegerin when compared to samples from patients with acute leukemia." (PMID 29250517, 2017).
acute lung injuries (2 papers, 2020 to 2023). "Pathologically, IL18-hUCMSC transplantation significantly enhanced the inhibition of inflammation, viral load, fibrosis, and cell apoptosis in acute lung injuries." (PMID 36707501, 2023).
allergic contact dermatitis (2 papers, 2012 to 2015). An inflammatory skin condition caused by an immune response to direct contact between the skin and an allergen. "Irritant and allergic contact dermatitis elicit similar early immune responses through the IL-1 pathway involving IL-18." (PMID 26690141, 2015). "It was suggested that this pathway involving IL-18 may induce skin sensitization and elicit the development of allergic contact dermatitis." (PMID 26690141, 2015).
amoebiasis (2 papers, 2021 to 2024). "These proteins were potentially regulated by STAT3 and mainly involved in IL-18 signaling and complement systems, RAS processing and amoebiasis." (PMID 34768771, 2021). "Furthermore, deregulated proteins were mapped in cell–cell contact zones and ciliary basal bodies, potentially regulated by STAT3 and involved in IL-18 signaling and complement systems, RAS processing, and amoebiasis." (PMID 38535507, 2024).
anaphylaxis (2 papers, 2022 to 2024). An acute hypersensitivity reaction that occurs from exposure to an allergen. "Genetic variations at the IL-18 locus (IL18R1 and IL18RAP) were associated with exercise-induced anaphylaxis, while MMP9 and OSM provide evidence for the involvement of innate immune pathways." (PMID 36569939, 2022).
anxiety disorder (2 papers, 2023 to 2024). A category of psychiatric disorders which are characterized by anxious feelings or fear often accompanied by physical symptoms associated with anxiety. "IL-18 is a compelling target in AUD and anxiety disorders, as it modulates biological functions during stress and recent studies reported greater circulating IL-18 levels in men than women during states associated with inflammation." (PMID 37566022, 2023). "In individuals with current depressive or anxiety disorders compared to healthy controls, elevated levels were observed in CRP, IL-6, IL-8, IL-18, MCP-1, MIP-1α, MIP-1β, MMP2, and TNF-β, while TNF-α, IL-10, IFN-γ, IL-2, and IL-4 levels either showed no significant elevation or were lower." (PMID 39273641, 2024).
aortic valve calcification (2 papers, 2022). "Notably, increasing levels of HMGB1 and IL-18 expression have been reported in patients with calcific aortic valve disease." (PMID 36497194, 2022). "IL-1β and IL-18 involve both innate and adaptive immune responses, performing a significant role in inflammatory development of atherosclerosis, cardiomyopathy, abdominal aortic aneurysm, calcific aortic valve disease, heart failure, and cardiovascular and cerebrovascular ischemic injury." (PMID 36204568, 2022). "Additionally, IL-18, one major product of NRLP3 inflammasome, has also been proved to be a potential mediator of aortic valve calcification." (PMID 36204568, 2022).
Ataxia (2 papers, 2010 to 2023). Ataxia refers to impaired coordination of voluntary muscle movement. "Three groups investigated the action of IL-18 in rodents following administration of KA, an agonist of the kainate receptors inducing seizure, cerebellar ataxia and exitotoxic mediated neuronal loss." (PMID 20113500, 2010). "In the cerebellum, where KA was demonstrate to induce ataxia partially via elevation of IL-1β, exogenous IL-18 was protective and played a positive role in the recovery from kainate-induced ataxia." (PMID 20113500, 2010). "Consistently, IL-18 KO and IL-18Rα KO mice show delay in recovery from kainate-induced ataxia." (PMID 20113500, 2010). "The first being the recognition that Il-18 and Il-1β, when their combined action was tested, may have antagonizing effects such as those occurring in fever and in kainate-induced cerebellar ataxia." (PMID 20113500, 2010). "At 3 weeks after the 3-AP injection, we did not observe any significant changes in the expression of Iba1, Il1b, Il18, or iNos, indicating no microglial and pro-inflammatory responses during the chronic phase of ataxia." (PMID 37047062, 2023).
autism (2 papers, 2016 to 2022). Persistent deficits in social interaction and communication and interaction as well as a markedly restricted repertoire of activity and interest as well as repetitive patterns of behavior. "Further studies are needed to clarify the cause that led to the increase of IL-18 in the brain of patients with autism and its downregulation in sera." (PMID 26728085, 2016). "Meanwhile, monocytes stimulated with LTA, neutrophils stimulated with IL-17A, and NK cells stimulated with IL-12/IL-18 or K562 cells showed differential responses in each of these cell types in autism, as compared with the controls." (PMID 36268027, 2022). "Patients with severe autism showed IL-18 serum levels lower than the other groups of patients and much lower than the healthy controls: severe autism mean 113.17 pg/mL; standard deviation 23.79; healthy controls mean 529.9 pg/mL; standard deviation = 274.1." (PMID 26728085, 2016). "IL-18 content decreased in the sera of patients with autism compared to healthy subjects and in Reeler sera compared to wild-type controls." (PMID 26728085, 2016). "IL-18 is reduced in sera but increased in the brain of patients with tuberous sclerosis with autism." (PMID 26728085, 2016). "The aim of the present work is to evaluate IL-18 serum levels in autism patients compared to healthy controls and in the murine experimental model of autism, the Reeler mice, compared to wild-type controls." (PMID 26728085, 2016). "Our data suggest that a chronic neuroinflammation is present in autism affected subjects, including IL-18 dysregulation." (PMID 26728085, 2016). "Our finding is in agreement with previous results detecting increased levels of IL-18 in the brain of an autism experimental mouse model consisting of an inbred strain with behavioral deficits similar to those found in children with autism." (PMID 26728085, 2016). "However, reduced levels of IFN-γ were observed in NK cells in autism after introducing an external stimulus, such as IL-12/IL-18 or K562 target cells." (PMID 36268027, 2022). "Moreover, quantitative analysis of IL-18 was performed in the sera and brain obtained from Reeler mice, an experimental model of autism." (PMID 26728085, 2016). "Therefore, patients with severe autism (CARS ≥37) show low levels of IL-18 but high levels of BDNF." (PMID 26728085, 2016).
brain hemorrhage (2 papers, 2008 to 2023). "In all three HPHC groups, CSF IL18 concentrations were significantly higher than control values, and the fetal intracranial haemorrhage group was significantly higher than SBA group." (PMID 19117508, 2008). "Although CIP alone, PEG alone, and CIP + PEG effectively inhibited IL-18 in serum, the results seem to suggest that IL-18 may not be associated with the IR-induced brain hemorrhage." (PMID 38162617, 2023).
brain inflammation (2 papers, 2012 to 2024). "Moreover, quercetin effectively suppressed the upregulation of Il-8, Il-6, Il-18, and Tnf-α in G. parasuis-infected bEnd.3 cells, thus mitigating the occurrence of brain inflammation." (PMID 38927100, 2024). "In addition, the mRNA expression levels of inflammatory cytokines (Il-6, Il-8, Il-10, Il-18, Il-1β, and Tnf-α) in GPS-infected mice were significantly increased compared to the control group (p < 0.05), which indicated that GPS successfully induced brain inflammation in mice." (PMID 38927100, 2024).
Burkholderia Infections (2 papers, 2018 to 2021). Infections with bacteria of the genus BURKHOLDERIA. "We and others have previously shown that processing and secretion of the mature form of IL-1β and IL-18 in response to Burkholderia infection was dependent on caspase-1." (PMID 29791511, 2018). "Recently it has been proposed that in the early phase of Burkholderia infection caspase-11 may act as an IFNγ-inducible effector mechanism because of its reliance on the IL-18-IFNγ axis for priming, which would place non canonical inflammasome downstream of canonical caspase-1 activation." (PMID 29791511, 2018).
Buruli ulcer (2 papers, 2023 to 2024). "In another study, IL-18 controlled skin inflammation in the progression of Buruli ulcers caused by Mycobacterium ulcerans." (PMID 38582846, 2024). "Using a mouse model of Buruli ulcer, we further demonstrated that IL-18 attenuates the progression of Buruli ulcer by controlling accumulation of neutrophils in the infected skin lesions." (PMID 37910490, 2023).
calcification (2 papers, 2014 to 2021). Process by which organic tissue becomes hardened by the physiologic deposit of calcium salts. "The results suggest that the serum IL-18 level of rats is positively correlated with the aortic calcium content, indicating that as the serum IL-18 level increases, the degree of aortic calcification is aggravated." (PMID 34901204, 2021).
Candidemia (2 papers, 2025). A form of invasive candidiasis where species of CANDIDA are present in the blood. "The proteomic profile in candidemia included eight of the most significantly upregulated DEPs: CXCL11, LAP-TGF beta-1, CD40, CXCL1, CXCL6, IL18, CXCL10, and uPA." (PMID 41229429, 2025). "The highest upregulated expressions in isolated candidemia included CXCL6, LAP-TGF beta-1, CXCL1, CXCL11, and CD5, while in candidemia with bacterial co-infection, CXCL11, CD40, uPA, CXCL1, CXCL10, and IL-18 were the most abundantly upregulated." (PMID 41229429, 2025).
Candidiasis (2 papers, 2012 to 2019). Infection with the organism Candida. "Of the cytokines induced, IL-1α, IL-1β, IL-6, IL-10, IL-17A, IL-18, IFN-γ, and TNF-α have been previously shown to play an important role in the pathogenesis of invasive candidiasis in vivo." (PMID 22916017, 2012).
central nervous system infection (2 papers, 2022). "Infections of the central nervous system, cell death, brain injury, and neurodegenerative disease all rely on IL-1β and IL-18." (PMID 36429017, 2022).
choroidal neovascularization (2 papers, 2021). An eye disorder described by the growth of new blood vessels that originate from the choroid through a break in the Bruch membrane into the sub–retinal pigment epithelium (sub-RPE) or subretinal space. "In contrast to the well-documented release of IL-1β in response to RPE para-inflammation there is considerable debate regarding whether IL-18 contributes to or protects from AMD-associated phenotypes including choroidal neovascularization (CNV)." (PMID 34071220, 2021). "This is consistent with an earlier study where IL-18–neutralizing antibodies were intravitreally injected in a laser-induced choroidal neovascularization (CNV) mouse model, and CNV development increased compared to non-injected mice." (PMID 33922669, 2021).
chronic granulomatous disease (2 papers, 2019 to 2020). Chronic granulomatous disease (CGD) is a rare primary immunodeficiency, mainly affecting phagocytes, which is characterized by an increased susceptibility to severe and recurrent bacterial and fungal infections, along with the development of granulomas. "Likewise, high levels of IL-18 and IFN-γ were detected in chronically inflamed tissue in chronic granulomatous disease." (PMID 32824088, 2020).
chronic GVHD (2 papers, 2006 to 2025). "IL-18 exerts its therapeutic effects on chronic GVHD through a tripartite mechanism: it induces donor-versus-host CD8+ CTLs, down-regulates MHC class II expression in host B cells, and reduces the population of donor CD4+ T cells." (PMID 40943537, 2025). "Several investigators have previously shown that treatment with IL-12 or IL-18 induced donor anti-host CTLs that eliminated host B cells in chronic GVHD mice." (PMID 16859527, 2006).
chronic pancreatitis (2 papers, 2022 to 2024). A chronic inflammatory process causing damage and fibrosis of the pancreatic parenchyma. "Stellate cells are capable of IL-18 production and, in the case of chronic pancreatitis, it has been shown that levels of IL-18 are increased following activation by lipopolysaccharide (LPS) or TGF-ß20." (PMID 35284826, 2022). "IL-18 levels are elevated in AP, and it has previously been suggested that this agent may play a role in acute and chronic pancreatitis together with several other interleukins." (PMID 35284826, 2022).
colorectal adenocarcinoma (2 papers, 2022). The most common type of colorectal carcinoma. "In the current study, we identified two L. strains, IBB109 and IBB417, which exhibit potent antiproliferative activity and stimulate the production of proinflammatory IL-18 cytokine in the colorectal adenocarcinoma cell line (CRC), Caco-2." (PMID 35694291, 2022).
Cyanosis (2 papers, 2017 to 2020). Bluish discoloration of the skin and mucosa due to poor circulation or inadequate oxygenation of arterial or capillary blood. "In line, no alterations in measured serum chemokine levels (IL-17A/F, IL-23, IL-18, CCL20, and CCL27) were observed either, confirming a weak relationship between serum cytokines and skin changes in all but most severely affected individuals." (PMID 33343564, 2020).